RAB31 (RAB31, member RAS oncogene family)
Diseases named in the same sentence as RAB31 in open-access papers (continued):
Sharing a sentence is not in itself a finding about the gene and the disease.
breast carcinoma (continued). "In addition, the C-terminal subunit of mucin-1 (MUC1-C), in concert with estrogen receptor α (ERα), was identified to activate Rab31 gene expression in breast cancer, whereby Rab31 upregulation, in turn, results in elevated MUC1-C levels, most likely by reducing its lysosomal degradation." (PMID 34906074, 2021). "However, to our knowledge, there has been no known association between Rab31 and effectors linked to breast cancer." (PMID 22792175, 2012). "However, little is known about the tumor biological effects of rab31 expression in breast cancer." (PMID 22920728, 2012). "The objective of this study is to explore whether the Cx43/Rab31 axis influences the biological characteristics and distant metastasis of triple-negative breast cancer via the autophagy signaling pathway, providing additional insights and experimental evidence for breast cancer treatment." (PMID 41463174, 2025). "Our results demonstrate that Rab31 is a potent modulator of the expression of TGF-ß and other components of the TGF-ß signaling pathway in breast cancer cells." (PMID 34906074, 2021). "Subsequent validation analyses by qPCR revealed a strong down-regulation of TGFB1 mRNA levels in response to increased Rab31 expression not only in CAMA-1 cells, but also in another breast cancer cell line, MDA-MB-231." (PMID 34906074, 2021). "In the present study, we demonstrate that Rab31 is a potent modulator of the expression of TGF-ß and other components of the TGF-ß signaling pathway in breast cancer cells." (PMID 34906074, 2021). "Commercially available profiler PCR arrays were applied to search for differentially expressed genes in Rab31 high- and low-expressing CAMA-1 breast cancer cells." (PMID 34906074, 2021). "Our findings indicate that Rab31, depending on its expression level, has a crucial impact on the expression of various components of the TGF-ß signaling pathway in breast cancer cells." (PMID 34906074, 2021). "Our results support a model in which the Rab31 gene is activated by both MUC1-C and ERα in breast cancer cells." (PMID 22792175, 2012). "Our results further demonstrate that Rab31 and MUC1 are significantly co-expressed in ER+ breast cancers." (PMID 22792175, 2012). "The expression pattern of rab31 in breast cancer cell lines MDA-MB-231, CAMA-1, and MDA-MB-435 upon stable transfection with the eukaryotic expression plasmid pRcRSV harboring the rab31 cDNA sequence was initially analyzed by Western blot analysis." (PMID 22920728, 2012). "Analysis of Rab31 expression in the GSE5764 dataset from 20 normal breast tissues and 10 breast tumors demonstrated that Rab31 mRNA levels are significantly higher in breast cancers as compared to normal breast tissue." (PMID 22792175, 2012). "As an essential regulator of vesicle and substance transport within the cytoplasm, Rab31 may promote the epithelial–mesenchymal transition (EMT) of tumor cells via autophagy, thereby affecting breast cancer progression." (PMID 41463174, 2025). "NUPR1 could also active autophagy and bind to the promoter regions of some autophagy-related genes, such as BECN1, GREB1, RAB31, PGR, CYP1B1, thereby regulating breast cancer metastasis and transcription." (PMID 37626099, 2023). "Recent research has shown that RAB31 is capable of inhibiting the TGF-β pathway by decreasing TGFB1 mRNA and antigen levels, thereby exerting an impact on the migration, invasion, and apoptosis of breast cancer cells." (PMID 37207166, 2023). "In addition to CAMA-1 cells, we also analyzed a second breast cancer cell line, MDA-MB-231, which expresses higher basal Rab31 protein levels compared to CAMA-1 cells." (PMID 34906074, 2021). "Furthermore, by immunohistochemical analyses of breast cancer tissue sections, both pAb RT3-IgG and pAb RT4-IgG (from animal #4) were qualified for detection of rab31." (PMID 22920728, 2012).
breast carcinoma (continued). "Rab31 expression is not restricted to ER+ breast cancer cells, indicating that ERα-independent mechanisms can also contribute to Rab31 gene transcription." (PMID 22792175, 2012). "There had previously been no available information on how the Rab31 gene is regulated in breast cancer cells, particularly those that express high Rab31 levels." (PMID 22792175, 2012). "Breast cancer cells displaying low (MDA-MB-231) or no (CAMA-1) endogenous rab31 expression were stably transfected with a rab31 expression plasmid." (PMID 22920728, 2012). "Moreover, Rab31 and MUC1-C protein levels were in lower abundance in MCF-10A cells relative to that in the breast cancer cells." (PMID 22792175, 2012). "Based on the present findings, patients with breast cancer that co-express MUC1-C and Rab31, and perhaps are resistant to tamoxifen, could be candidates for the targeting of MUC1-C with this agent." (PMID 22792175, 2012). "Comparing cell lines with differential endogenous rab31 levels, again the strongest effects were detected in breast cancer cell lines not showing any detectable endogenous rab31 expression (CAMA-1 and MDA-MB-435)." (PMID 22920728, 2012). "During invasion and metastasis, Rab31-triggered downregulation of TGF-ß may be lost, since, e.g., elevated levels of TGF-β—leading to an EMT-like phenotype of the cancer cells—have been found at invasive fronts in human breast cancer tissues." (PMID 34906074, 2021). "The results obtained with the xenograft animal models, therefore, may not directly mirror the malignant features of rab31-, uPAR-del4/5- or HuR overexpressing tumors in human breast cancer." (PMID 22920728, 2012). "Indeed, silencing of Rab31 in breast cancer cells was associated with a decrease in MUC1-C protein, but not transcripts, indicating that Rab31 might prevent processing of endosomal MUC1-C for degradation in lysosomes." (PMID 22792175, 2012).
gastric cancer (15 papers, 2019 to 2025). A primary or metastatic malignant neoplasm involving the stomach. "The expression of RAB31 increased with gastric cancer progressed, and cells overexpressing RAB31 exhibited an enhanced capacity for migration." (PMID 40708696, 2025). "The activation of Twist1 by Rab31 facilitated through STAT3 stimulation and MUC-1 suppression reveals a novel Rab31/STAT3/MUC-1/Twist1/EMT axis implicated in the drug resistance and metastatic potential of gastric cancer." (PMID 39309860, 2024). "Similar studies in glioblastoma, cervical and gastric cancer confirm the role of Rab31 in regulating apoptosis with overexpression of Rab31 correlated with decreased expression of BAX, cleaved caspase 3 and PARP, concomitant with increased expression of BCL-2." (PMID 31973201, 2020). "RAB31 may also be involved in the formation of invadosomes in gastric cancer by promoting actin dot formation under the fibronectin-induced signal in EHT and thus playing an important role during invasion and modulating pathogen virulence." (PMID 39228892, 2024). "Recently, Rab31 was reported to function as an oncogene in gastric cancer tumorigenesis and may serve as a therapeutic target in gastric cancer, which is in line with our previous study." (PMID 36781842, 2023). "Similarly in gastric cancer cells, KD of Rab31 by siRNA reduced expression of the BCL-2, Hedgehog (Hh) signaling transcript GLI1 while increasing BAX protein levels." (PMID 31973201, 2020). "The miR-30c-2-3p acts on RAB31 and regulates the GLI1 signaling pathway in gastric cancer tumorigenesis and development." (PMID 34067819, 2021).
glioblastoma (10 papers, 2013 to 2022). The most malignant astrocytic tumor (WHO grade IV). "Several studies have demonstrated that RAB31 is correlated with prognosis in patients with breast, ovarian, liver cancer, and glioblastoma." (PMID 29957874, 2018). "Rab31, another member of Ras superfamily, was reported to promote the malignant progression of glioblastoma and cervical cancer through inducing epithelial-mesenchymal transition." (PMID 30064475, 2018). "Meta-analysis of microarray studies using Bayesian network analysis also found Rab31 to be among 10 genes that are most influential in the development of glioblastoma multiforme." (PMID 25472813, 2015). "Moreover, RAB31 is on the list of genes with the greatest influence on the development of the highest-grade astrocytoma, glioblastoma multiforme." (PMID 36231068, 2022). "Knockdown of Rab31 expression in glioblastoma cells suppressed tumor growth in a nude mouse model." (PMID 34906074, 2021). "IPA connections of Grade IV Glioblastoma Markov genes reveled direct interactions between CD99 and ANXA2, and EGFR and RAB31 genes." (PMID 23737970, 2013).
cervical cancer (6 papers, 2015 to 2024). A primary or metastatic malignant neoplasm involving the cervix. "Next, cervical cancer cells with Rab31 knockdown or overexpression were constructed to explore the role of Rab31 in cervical cancer metastasis and underlying molecular mechanism." (PMID 34975321, 2022). "Additionally, Rab31 inhibited the degradation of MAPK6, and MAPK6 overexpression restored the reduced invasion capability of cervical cancer cells caused by Rab31 knockdown." (PMID 34975321, 2022). "Rab31 is also among the genes that associate with tumour progression in centrosomal protein transforming acidic coiled coil (TACC) 3 overexpressing HeLa cells as a model of cervical cancer." (PMID 25472813, 2015). "Higher expression of RAB31 was significant associated with shorter overall survival in pancreatic cancer and RAB31 knockdown could inhibited the epithelial-mesenchymal transition and cytoskeletal rearrangement in cervical cancer cells." (PMID 36085041, 2022). "Rab31 is overexpressed in cervical cancer tissues and enhances migration and invasion of cervical cancer cells by promoting epithelial mesenchymal transition (EMT) and affects the cytoskeletal rearrangement in an MAPK6-dependent manner." (PMID 38695990, 2024). "To investigate the mechanism by which Rab31 regulates the invasion of cervical cancer cells, we used the BioGRID database to search for molecules that interact with Rab31." (PMID 34975321, 2022). "Because Rab31 promoted the migration and invasion of cervical cancer cells, we detected the expression of classic EMT markers." (PMID 34975321, 2022). "Rab31 promoted the invasion of cervical cancer cells by enhancing EMT and affected the cytoskeletal rearrangement." (PMID 34975321, 2022). "Accumulating reports has indicated that RAB31 is widely involved in the prognosis of various cancers, including pancreatic cancer, cervical cancer and others." (PMID 36085041, 2022). "Our mass spectrometry data showed that the Ras-associated binding protein Rab31 was upregulated by HPV; however, little is known regarding the role of Rab31 in the metastasis of cervical cancer cells." (PMID 34975321, 2022). "Overall, these data suggest that Rab31 is a key molecule for cervical cancer metastasis, and that Rab31 knockdown reduces the capability of cervical cancer cells to metastasize far in vivo." (PMID 34975321, 2022). "Taken together, these results suggest that Rab31 is highly expressed in cervical cancer tissues and cells and that both high-risk HPV E6 and E7 upregulate Rab31 expression." (PMID 34975321, 2022). "To explore the effect of Rab31 on the metastatic capability of cervical cancer cells in vivo, we injected Rab31-knockdown SiHa cells and control cells into the tail vein to establish an in vivo tumor metastasis model." (PMID 34975321, 2022). "We showed that Rab31 level was higher in HPV-positive cervical cancer cells than in HPV-negative cervical cancer cells." (PMID 34975321, 2022). "The current study confirmed that Rab31 was aberrantly highly expressed in cervical cancer tissues and cells, and that both high-risk HPV E6 and E7 proteins upregulated Rab31." (PMID 34975321, 2022). "In this study, we showed that Rab31 was highly expressed in cervical cancer tissues and cells, and both HPV E6 and E7 promoted the expression of Rab31." (PMID 34975321, 2022). "We showed that Rab31 knockdown in HeLa and SiHa cells inhibited while Rab31 overexpression in C33A cells promoted the invasion of cervical cancer cells." (PMID 34975321, 2022). "Transwell assay showed that Rab31 knockdown inhibited the migration and invasion of cervical cancer cells." (PMID 34975321, 2022). "Rab31 knockdown inhibited while Rab31 overexpression promoted the migration and invasion capabilities of cervical cancer cells." (PMID 34975321, 2022).
cervical cancer (continued). "To explore the role of Rab31 in cervical cancer, we first examined the mRNA and protein expression levels of Rab31 in HaCaT and four cervical cancer cell lines, HeLa, SiHa, CaSki and C33A, using qRT-PCR and Western blotting, respectively." (PMID 34975321, 2022). "We showed that MAPK6 overexpression partially restored the migration potential of Rab31-knockdown cervical cancer cells." (PMID 34975321, 2022). "Next, we explored the effect of Rab31 knockdown on the migration and invasion capabilities of cervical cancer cells." (PMID 34975321, 2022). "We conclude from these results that the pro-invasive effect of Rab31 in cervical cancer is partially dependent on MAPK6." (PMID 34975321, 2022). "In conclusion, Rab31 plays a crucial role in cervical cancer metastasis by inhibiting MAPK6 degradation." (PMID 34975321, 2022). "Rab31 knockdown inhibited cervical cancer metastasis to the lungs and livers." (PMID 34975321, 2022). "Rab31 is highly expressed in HPV18-positive cervical cancer HeLa and HPV16-positive SiHa cells." (PMID 34975321, 2022). "We performed rescue experiments to further determine whether Rab31 promoted the invasion of cervical cancer cells in a MAPK6-dependent manner." (PMID 34975321, 2022). "In the present study, we examined the Rab31 expression levels in cervical cancer tissues and cells." (PMID 34975321, 2022). "In the present study, we revealed increased Rab31 expression in cervical cancer tissues and cells." (PMID 34975321, 2022). "We also investigated whether MAPK6 affected the development of cervical cancer and showed that MAPK6 knockdown inhibited the viability, migration and invasion of cervical cancer cells as well as Rab31-overexpressing cells." (PMID 34975321, 2022). "Therefore, we used HPV-positive HeLa and SiHa cells as well as HPV-negative C33A cells to investigate the effect of Rab31 on cervical cancer invasion." (PMID 34975321, 2022). "Taken together, these data indicate that Rab31 may act as an inducer of cell invasion in cervical cancer." (PMID 34975321, 2022). "Rab31 expression in HPV-negative cervical cancer C33A cells was relatively low." (PMID 34975321, 2022). "Our study provides novel insights into the molecular mechanism of cervical cancer invasion and metastasis and suggests that Rab31 may be a new potential target in cervical cancer." (PMID 34975321, 2022). "Finally, a xenograft mouse model showed that Rab31 knockdown in cervical cancer cells led to reduced tumor growth and impaired lung and liver metastasis in vivo." (PMID 34975321, 2022). "Additionally, we observed significantly impaired tumor growth and metastatic dissemination of Rab31-knockdown cervical cancer cells to the lung and liver in a xenograft mouse model." (PMID 34975321, 2022). "Our data provide novel insights into the role of Rab31 in cervical cancer progression." (PMID 34975321, 2022). "In addition to MAPK6, other molecules or pathways may be responsible for Rab31-mediated migration and invasion of cervical cancer cells." (PMID 34975321, 2022). "However, little is known regarding the tumor biological effects of Rab31 in cervical cancer." (PMID 34975321, 2022). "Thus, Rab31 may serve as a novel therapeutic target to manage cervical cancer." (PMID 34975321, 2022). "Additionally, Rab31 knockdown inhibited the epithelial-mesenchymal transition (EMT) and cytoskeletal rearrangement in cervical cancer cells." (PMID 34975321, 2022). "Both the transcription and protein levels of Rab31 were the lowest in non-cancer HaCaT cells and increased in cervical cancer cells." (PMID 34975321, 2022). "Additionally, siRNA targeting HPV18 E6/18 E6E7 or 16 E6/16 E6E7 significantly decreased Rab31 expression in HPV18-positive HeLa or HPV16-positive SiHa and CaSki cervical cancer cells." (PMID 34975321, 2022).
cervical cancer (continued). "We further investigated the mRNA level of Rab31 in 55 non-cancer cervical tissues and 66 cervical cancer tissues collected from the Department of Pathology, Qilu Hospital of Shandong University." (PMID 34975321, 2022). "The expression of Rab31 in cervical cancer tissues was significantly higher than that in non-cancer tissues." (PMID 34975321, 2022).
pancreatic cancer (6 papers, 2020 to 2022). "Elevated Rab31 in pancreatic cancer is associated with reduced overall survival." (PMID 34975321, 2022). "For example, the combination of SRPX2 and RAB31 may be an important prognostic marker for pancreatic cancer, with a 3-year AUC value of 0.748." (PMID 33550277, 2021).